IL6 (interleukin 6)
Diseases named in the same sentence as IL6 in open-access papers (continued):
Sharing a sentence is not in itself a finding about the gene and the disease.
breast cancer (continued). "In this complex scenario of multiple cytokines driving endocrine resistance in HRG-overexpressing ER+ breast cancer cells, the sole blockade of IL-8 bioactivity might become inadequate in the presence of an augmented availability of IL-6 downstream of the HRG-activated HER2/HER2 oncogenic unit." (PMID 33086721, 2020). "Furthermore, treatment with recombinant IL-6 and IL-8 could effectively promote the growth of breast cancer epithelial cells." (PMID 32411704, 2020). "Administration of IL‐6 and oncostatin M has been shown to suppress breast cancer growth in vitro, suggesting that IL‐6 and other myokines could have a direct role in reducing cancer progression by modulating key signaling pathways involved in cancer cell proliferation." (PMID 33207085, 2020). "AMPK is noticed to regulate the expression of IL-6 and IL-8 in adipocytes, suggesting that targeting AMPK in adipocytes could be a novel way to modulate obesity-related adipokine production associated with insulin resistance and breast cancer progression." (PMID 32201525, 2020). "In addition, our evidence also indicated that G-CSF could cooperate with other CAA-secreted factors, such as IL-6 and GM-CSF, to activate Stat3 signaling and promote breast cancer cell migration." (PMID 32242230, 2020). "In addition, there was also evidence showing that IL-6 expression could be modulated by CK2 in inflammatory breast cancer cells." (PMID 30992075, 2019). "Similar to IL-10, IL-6 may act to promote or suppress breast cancer." (PMID 30640711, 2019). "However, the studies of IL-6/IL-6R/gp130 immunotherapy for treatment of breast cancers are limited." (PMID 30885232, 2019). "Collectively, we noticed that IL-6 could enhance the expression of PIM1 in breast cancer cells." (PMID 30989585, 2019). "It has been reported that high levels of IL-6 and TNFα are correlated with strong tumor invasiveness and poor prognosis of breast cancer, and our results show that TNFα induced GM-CSF in cancer cells, suggesting that TNFα may enhance tumor growth through the induction of GM-CSF." (PMID 31581558, 2019). "Similarly, YAP confers some CSC properties, such as sphere formation and chemoresistance, on hepatocellular carcinoma, esophageal cancer, osteosarcoma, and basal-like breast cancer cells by coordinating the expression of interleukin 6 (IL-6) and stemness marker proteins such as SOX2, SOX9, and CD90." (PMID 30800215, 2019). "Therefore, we speculate that there are different IL-6-mediated HIC1 regulatory mechanisms in different breast cancer cell lines." (PMID 31795965, 2019). "In conclusion, IL-6 is involved in the proliferation, metabolism, metastasis, invasion, and angiogenesis of various tumors and has been found to have high expression of IL-6 in various tumors, such as breast cancer, colorectal cancer, prostate cancer, lung cancer, ovarian cancer, and so on." (PMID 31832112, 2019). "Our laboratory also found that osteoblasts are altered by breast cancer metastases in late-stage disease and undergo a stress response to produce a classic set of cytokines that are maintenance factors for metastatic breast cancer cells: IL-6, IL-8, MCP-1, GRO-alpha, and VEGF." (PMID 30813947, 2019). "Similarly, breast cancer-derived exosomes can induce increases in mRNAs of pro-inflammatory cytokines such as interleukin (IL)-6, tumor necrosis factor (TNF), granulocyte colony stimulating factor (G-CSF) and chemokine CCL2, through a Toll-like receptor (TLR)-2 stimulation and NF-κB in macrophages." (PMID 30895170, 2019). "Whether this is a general mechanism regulating the secretion of IL-6 has been questioned, since in two breast cancer cell lines, genetic inhibition of autophagy decreased IL-6 secretion in triple negative cell lines, but increased IL-6 secretion in a luminal breast cancer cell line." (PMID 31554173, 2019). "Moreover, IL-6 cytokine leukemia inhibitory factor (LIF) was hypothesized to facilitate breast cancer dormancy in the bone." (PMID 30456206, 2018).
breast cancer (continued). "For instance, using mammosphere assay as a readout for CSCs activity, Sanguinetti and coworkers found that IL-6 induces stem-like features by stimulating the Notch-3-dependent upregulation of the carbonic anhydrase IX gene and promoting a hypoxia-resistant/invasive phenotype in breast cancer cells." (PMID 29996493, 2018). "Hence, paracrine IL-6 signalling may be a key regulator of adipocytes induced proliferation, migration and invasion in breast cancer cells, through phosphorylation and nuclear localization of STAT3." (PMID 29891854, 2018). "However, IL-6 knockdown exclusively displayed significant inhibition on 4T1 tumor growth and metastasis in vivo which indicated that microenvironment plays a vital role in breast cancer development and progression." (PMID 30083161, 2018). "Collectively, our data suggest that the simultaneous expression of IL-6 and RANTES produces a more aggressive phenotype in breast cancer cells and provide evidence that IL-6 and RANTES might represent potential targets for novel therapeutic strategies aimed to block the tumor-stroma interaction." (PMID 29707128, 2018). "However, in breast cancer, IL-6 promotes the activities of STAT3." (PMID 30325954, 2018). "Thus, we speculate that IL-6 maybe a common regulating cytokine in adipocyte-breast cancer cell interaction." (PMID 29891854, 2018). "Therefore, blocking the IL-6 signaling pathway might be a promising therapeutic strategy for breast cancer treatment." (PMID 30083161, 2018). "IL-6 was significantly higher among the chemotherapy than vehicle groups at all time points (p < 0.0001), suggesting a sustained effect of chemotherapy on this cytokine, as has been noted in breast cancer patients undergoing doxorubicin plus cyclophosphamide treatment." (PMID 30567351, 2018). "Recent evidence showed that IL-6 played critical roles in cancer development and progression by regulating the tumor microenvironment, which threw new light on the molecular mechanism regulating the IL-6-induced growth and metastasis of mammary carcinoma in vivo." (PMID 30083161, 2018). "Together, these data indicate that IL-6 signaling contributes to cancer malignancy through the promotion of CSCs growth and survival, and that targeting IL-6 may offer benefits for hepatoma, glioma and breast cancer patients." (PMID 28927416, 2017). "It was demonstrated recently that in breast cancer, EzH2 promotes a constitutive activation of NF-κB that leads to an increase in its target genes expression, including IL-8, IL-6 and TNF-α cytokines, suggesting that it might be doing the same in our model of CAC." (PMID 29285251, 2017). "Moreover, CXCR2+ MDSCs could induce breast cancer cells EMT via IL-6, and promote activated CD4+ or CD8+ T cells exhaustion partially via IFN-γ." (PMID 29383101, 2017). "We therefore hypothesized that, given the production of Shh and IL-6 in breast tumor microenvironment, serum Shh and IL-6 are abundant and might be detectable in the general circulation, and, if highly abundant in blood sera, would specify poor outcome and prognosis in breast cancer patients." (PMID 28496132, 2017). "Previous studies have proventhat IL-6 can be characterized as a pro-inflammatory cytokine that stimulates immuneresponses and promotes tumorigenesis and metastasis in a wide range of cancers, e.g.lung cancer, cervical cancer, breast cancer, ovarian cancer, and renal cellcarcinoma." (PMID 28659496, 2017). "However, curcumin pre-treatment for 5 days in cisplatin-treated rats significantly reduced the levels of TNF-α (p < 0.001), IL-6 (p < 0.01), and IL-8 (p < 0.05) whereas significantly improved the level of IL-10 (p < 0.001) as compared to cisplatin-treated breast cancer rats." (PMID 28420987, 2017). "Sullivan and colleagues first demonstrated in human breast cancer that IL-6 could induce EMT." (PMID 28061440, 2017).
breast cancer (continued). "IL-6 is involved in the proliferation, differentiation and apoptosis resistance of various malignant tumor cells, such as multiple myeloma, lung cancer, renal cell carcinoma, breast cancer, colorectal cancer, endometrial cancer, cervical cancer, and ovarian carcinoma." (PMID 28927416, 2017). "However, whether Shp2 is involved in IL-6-signaling-promoted breast cancer EMT and progression, remains uncertain." (PMID 28208810, 2017). "Deficient perivascular coverage of tumor blood vessels in a PDGFRβ−/− mouse model of breast cancer resulted in recruitment of MDSCs contributing to an immunosuppressive tumor microenvironment mediated by the induction of the protumorigenic cytokine IL-6 in malignant cells." (PMID 28878242, 2017). "Thus, given the central role of the IL-6/IL-11–STAT3 pathway in the regulation of breast cancer progression and metastasis, blocking of this pathway by MH may underlie the latter’s multi-faceted effects that are reported in this study." (PMID 28856117, 2017). "However, whether Shp2 is involved in IL-6-signaling-promoted breast cancer EMT and progression, remains undefined." (PMID 28208810, 2017). "Therapeutic targeting of the receptors of IL-6 and IL-8 using Tocilizumab and Reparixin significantly decreases the expression of the Arp2/3 complex in a mouse xenograft model and decreases metastasis of breast cancer cells to the lungs, liver, and lymph nodes." (PMID 28548090, 2017). "Therefore, combination therapy with ER antagonists and IL-6/IL-6R/gp130 inhibitors may provide a novel therapeutic strategy for ER+ breast cancers." (PMID 26840088, 2016). "However, it remains unclear whether increased IL-6 expression determines the sensitivity of HER2-positive breast cancer cells to lapatinib." (PMID 27694691, 2016). "However, these SERMs may have potential effects against breast cancer via IL-6 signaling in addition to ER-modulating mechanisms." (PMID 26840088, 2016). "In addition, IL-6 cooperates with HER2 to promote breast cancer and may be involved in the resistance of HER2-positive tumors to anti-HER2 therapy." (PMID 27602583, 2016). "Furthermore, IL-6 has been proved to play a vital role in breast cancer progression and prognosis." (PMID 27231908, 2016). "Thus, it has been suggested that anti-IL-6 therapies, alone or in combination with other therapies, may be efficacious to treat breast cancers." (PMID 27602583, 2016). "Hence, the aim of this study was to evaluate the associations between two common pro-inflammatory cytokine gene polymorphisms namely, IL6-174 (rs1800795 G>C) and TNF-308 (rs1800629 G>A), and chemotherapy-associated cognitive impairment (CACI) among Asian early-stage breast cancer patients." (PMID 27701469, 2016). "However, whether IL-6 is a downstream effector of A1CF (-8aa) or A1CF in breast cancer progression remained unclear." (PMID 27231908, 2016). "IL-6 appears to play a critical role in the growth and metastasis of breast cancer cells, renewal of breast cancer stem cells (BCSCs), and drug resistance of BCSCs, making anti–IL-6/IL-6R/gp130 therapies promising options for the treatment and prevention of breast cancers." (PMID 26840088, 2016). "However, preclinical and clinical studies on the effectiveness of IL-6 targeting agents for breast cancer are limited despite the substantial body of evidence indicating that high levels of IL-6 contribute to the poor prognosis and promotion of breast cancer." (PMID 26840088, 2016). "In addition, recent studies have revealed that certain cancer cells can also produce IL-6 and that serum IL-6 levels correlate with the progression of several different carcinomas, such as gastric, esophageal squamous cell, lung, prostate, and breast cancers, as well as CRC." (PMID 26858756, 2016).
breast cancer (continued). "Conjointly, the role of IL-6 in breast cancer has to be further clarified since recent studies revealed that IL-6 appears to play a critical role in the growth and metastasis of breast cancer cells, renewal of breast cancer stem cells and drug resistance of breast cancer stem cells." (PMID 27187369, 2016). "Interestingly, monocytes from patients with early breast cancer produced similar amounts of cytokines (IL-8, IL-6, IL-1β and TNF) as those observed in patients with advanced disease (LRR/MBC), suggesting that monocytes are functionally affected already early in the disease." (PMID 25992611, 2015). "However, few data are yet available on the relationship between IL-6 and stem/progenitor cells, which may fuel the genesis of breast cancer in vivo." (PMID 25881039, 2015). "Finally, we present data regarding the autocrine IL-6 loop in breast cancer cells." (PMID 25881039, 2015). "Moreover, patients with breast cancer liver metastases had significantly higher IL-6 levels." (PMID 25885919, 2015). "We wanted to determine whether YB-1 could activate IL-6 expression in breast cancer cells." (PMID 26512918, 2015). "Moreover, the IL-6/STAT3/JAK2 pathway is involved in the maintenance of stem cell–like cancer cells because CD44+CD24+ and CD44+CD24− breast cancer cells have high phospho-STAT3 via their expression of genes such as IL6, PTGIS, and HAS1, which activate an autocrine loop." (PMID 26515594, 2015). "In addition to having a pivotal role in basal breast cancer growth and metastasis, the secreted factors implicated in our previous study (IL6, CSF2, CCL5, VEGFA, and VEGFC) may also serve critical roles in other subtypes of breast cancers." (PMID 26173622, 2015). "Since breast cancer patients with elevated serum IL-6 have poorer prognosis, Actemra may not be a practical therapy in these patients, however alternative approaches to reduce IL-6 signaling may prove efficacious." (PMID 26268945, 2015). "To determine whether CAF-stimulated migration and interaction with MCF10.DCIS cells could be inhibited by blocking IL-6, we co-cultured MCF10.DCIS cells with two human breast carcinoma-associated fibroblast lines WS-12Ti or CAF40TKi, in the presence of IL-6 nAb or an isotype control antibody." (PMID 26268945, 2015). "Furthermore, conditioned medium from senescent MSCs could activate STAT3, the main downstream transcription factor of IL-6, in breast cancer cells, and the activation could be blocked by an IL-6-neutralizing antibody." (PMID 25419563, 2014). "Moreover, we recently demonstrated that different factors produced by MSCs, such as vascular endothelial growth factor A (VEGF) and IL6, may cooperate in promoting breast cancer cell migration." (PMID 25344915, 2014). "Moreover, IL-6 has also been correlated with cancer treatment resistance where modulating the IL-6 pathway directly affects the cellular resistance to treatment, including breast cancer, ovarian cancer and esophageal cancer." (PMID 23806095, 2013). "Thus, in this study, we provide evidence that MDSCs potentiated by metastasizing breast cancer cells directly enhance the aggressiveness of cancer cells though trans-signaling by upregulating both IL-6 and sIL-6Rα secretion in primary tumor sites and the metastatic lung." (PMID 24021059, 2013). "Finally, we propose a mechanism that could explain the invasiveness of ‘triple-negative’ breast cancer cell line MDA-MB-231 via a positive feedback loop of IL-6 secretion and maintenance." (PMID 23372803, 2013). "Moreover, IL-6 is capable of converting dormant breast cancer cells into an actively growing tumor." (PMID 24156030, 2013). "Cytokines such as MCP-1 and IL-6 may promote breast cancer progression." (PMID 23552194, 2013). "Also, studies evaluating IL-6 expression in mammary carcinomas, show contradictory results." (PMID 23145063, 2012). "Thus IL-6 production was downstream of TG2 activity in the breast cancer cells." (PMID 21967801, 2011).
breast cancer (continued). "Therefore, agents that inhibit the production of IL-6 could improve the efficacy of vaccination or chemotherapy against breast cancer." (PMID 18728665, 2008). "The results from our study do not support the hypothesis that the cytokine polymorphisms studied [IL1A +4845G>T, IL1B -511C>T, IL1B +3954C>T, IL1RN +2018T>C, IL4R -1902A>G, IL6-174G>C and IL10-1082G>A] are associated with breast cancer susceptibility and severity." (PMID 16842617, 2006). "Previous studies have identified several FOSL1‐mediated stemness inducers such as IL‐6/STAT3 and SNAI3 in breast cancer, suggesting that drug resistance is induced by the FOSL1‐IL‐6/STAT3‐stemness axis." (PMID 41556041, 2026). "MCs are derived from common progenitor cells and are activated in breast cancer angiogenesis, where they generate TNF, proteases, IL-1, and IL-6, which induce inflammation." (PMID 41596472, 2026). "MCF-7 breast cancer cells yielded comparable results, with a significant increase in TNT observed in cells treated with TGFβ-1, IL-6, and HGF." (PMID 41750361, 2026). "Serum YBX1 can be used as a molecular marker in patients with bone metastases from breast cancer, and serum YBX1-positive patients also have higher expression of IL-6, a known osteogenesis-inducing molecule." (PMID 41507135, 2026). "For two pro-inflammatory proteins crucial in breast cancer metastasis and EMT process, IL6 and CXCL8, semi-quantitative results of the Human Profiler Cytokine Array Kit were verified by ELISA in a wider range of concentrations and incubation times." (PMID 40141419, 2025). "We focused on IL-2, IL-6, IL-10, and TNF-α due to their well-documented relevance in breast cancer immunobiology, as reported in previous studies." (PMID 40869161, 2025). "Yenidogan et al207 conducted a randomized trial and found that elderly breast cancer patients who received β-glucan treatment had significantly lower levels of TNF-α and IL-6." (PMID 40584290, 2025). "IL-6 and IL8, secreted by senescent fibroblasts in breast cancer, drive epithelial-to-mesenchymal transition in cancer cells and enhance the invasiveness of multiple cultured cancer cell lines." (PMID 40100482, 2025). "Silibinin also regulates cytokine secretion, increasing IL-12 and IFN-γ levels while reducing TGF-β, SDF-1, IL-6, and TNF-α, all of which play crucial roles in immune regulation and anti-cancer immunity in 4T1 breast cancer bearing mice." (PMID 40490812, 2025). "ELISA revealed that the levels of cytokine IL6 in MG+4T1-CM and MG + MDA-MB-231-CM were significantly higher than those of cytokine IL6 in the MG or breast cancer cell group (P < 0.001)." (PMID 40444044, 2025). "For instance, in the context of breast cancer, aged fibroblasts secrete factors from the SASP, including IL-6 and IL-8." (PMID 41294748, 2025). "The study suggests that DMBA-induced breast cancer model rats respond differently to treatment with CBD, THC, or HL in terms of IL-6 levels." (PMID 40008130, 2025). "In this study, the objective was to evaluate the prognostic relevance of serum levels of IL-6 and TNF-alpha in survival and treatment response in women with breast cancer." (PMID 40558287, 2025). "Multicenter RCTs should also explore the impact of exercise interventions on biomarkers like CRP, IL-6, and TNF-α for breast cancer patients to validate broader applicability of results." (PMID 41280723, 2025). "It has been reported that in the presence of IL-6 secreted from adipocytes, breast cancer cells (MDA-MB-468 and MCF-7) exhibited enhanced migratory and invasive capacity as a consequence of IL-6 protein and SNAI1 transcription upregulation." (PMID 40371393, 2025). "Similar to our findings, dysregulated plasma levels of IL-6, IL-8 and TNF-α have also been observed in patients with CRCI in breast cancer and hematological malignancies." (PMID 40597835, 2025).